LEPR (leptin receptor)
Diseases named in the same sentence as LEPR in open-access papers (continued):
Sharing a sentence is not in itself a finding about the gene and the disease.
Obesity (continued). "Alternatively, the distinct etiology of obesity, such as the “obesity” driven by different master regulators or lifestyles (e.g., deficiency in Leptin receptor) may exhibit different status of oxygen concentration in adipose tissues." (PMID 36496995, 2022). "Dysregulation of leptin or its receptor (LEPR) causes severe obesity and diabetes." (PMID 36189793, 2022). "Mutations in leptin and LEPR genes have been reported to cause obesity in human and animal models." (PMID 35650533, 2022). "Most LEPR SNPs have been assessed as potential modifying factors of the response to diet or of survival in cancer patients according to their BMI, with associations between these polymorphisms and obesity and CRC being contradictory or inconsistent." (PMID 35563103, 2022). "Additionally, other novel LEPR mutations were detected both in two unrelated girls with severe obesity and in obese children from inbred Pakistani families, which constitute 3% of the whole cohort of severely obese children." (PMID 34208585, 2021). "Thus, leptin receptor blockade represents a potential pharmacotherapy for obesity-associated hypertension." (PMID 34276408, 2021). "Obesity might also be associated with hyperleptinaemia, which reflects a state of leptin resistance involving leptin and molecular pathways downstream of LEPR, or with leptin deficiency, which might be either complete or heterozygous." (PMID 34208585, 2021). "Moreover, the obesity is promoted by the fa leptin receptor mutation, but this is not common cause of obesity among humans." (PMID 33716794, 2021). "Experimental evidence demonstrated that an obesity-causing mutation in the leptin receptor promoted the development of CRC in mice model with APC mutation, an important initiating event of subtype 1, whereas in MSI mice model, diet or weight change had no such effect." (PMID 33442661, 2021). "Therefore, leptin treatment is useful for treating obesity, while congenital leptin- or leptin receptor deficiency can lead to hyperphagia and early-onset obesity." (PMID 34684625, 2021). "It is plausible that in an obesogenic environment, individuals heterozygous for LEP or LEPR variants may preferentially develop obesity with increasing age if compared to wt/wt subjects." (PMID 34448070, 2021). "The prevalence of pathogenic LEPR mutations in a cohort with severe, early-onset obesity was 3%." (PMID 34390703, 2021). "Results of these studies will enable a deeper understanding of leptin physiology and possible therapeutic applications as well as prevention of obesity and metabolic disease associated with leptin and leptin receptor heterozygosity or partial leptin deficiency." (PMID 34448070, 2021). "Genetic factors may also influence leptin levels, since mutation in the leptin-receptor gene is associated with obesity." (PMID 35052684, 2021). "For some obesity rodent models, we found no example of acupuncture studies: this is the case for SHRSP/IDmcr-fas rats, db/db mice (loss of function mutation in the gene encoding leptin receptor), KK/HlJ mice, high-fat diet induced obesity Swiss mice, and C57BL/6NCrl mice." (PMID 34630614, 2021). "Third, many studies have shown that the polymorphism in LEPR is associated with the levels of blood glucose, insulin, leptin, and triglyceride, and LEPR deficiency can directly lead to the accumulation of fat, resulting in obesity." (PMID 34419151, 2021). "db/db mice are a type of spontaneous obese diabetic mice whose leptin receptor mutation leads to leptin signaling pathway dysfunction; they also appear with obesity and diabetes-related symptoms such as insulin resistance, significant increases in blood glucose levels, and hepatic steatosis." (PMID 34256832, 2021). "Genetic studies demonstrated that single nucleotide polymorphisms (SNPs) in the MC4R, LEP, and LEPR genes could be linked with obesity." (PMID 34205732, 2021).
Obesity (continued). "Given that db/db mice are leptin receptor-deficient models that show features of obesity and leptin resistance, we investigated whether daily intake of WHS alleviates adiposity in genetically obese db/db mice in this study." (PMID 34684625, 2021). "Studies suggest that obesity-induced bone loss is due to skewed differentiation of LepR+ cells toward adipogenesis instead of osteogenesis; however, several cytokines produced both by AT and immune cells can negatively impact maintenance of the OB population and bone remodeling." (PMID 33554957, 2021). "In addition, ameta-analysis study in Chinese population showed that two variants of LEPR(R223Q and P1019P) are related to obesity." (PMID 33687165, 2021). "Importantly, MSM has been found to improve insulin sensitivity and blood glucose levels in mouse models of diet-induced obesity as well as leptin receptor-deficient (db/db) mice." (PMID 34684621, 2021). "Moreover, emerging data from genome-wide association studies revealed that several genetic variants of LEPR were associated with obesity development." (PMID 34208585, 2021). "Our data may stimulate further human genetics research to test the hypothesis that compound heterozygous variants in the Leptin and or LEPR genes contribute to an increased obesity risk in subpopulations." (PMID 34390703, 2021). "This study used Db/Db mice with leptin receptor deficiency and Western diet to test the hypothesis that type 2 diabetes and obesity would develop dysfunctional vertebral structure, IVD morphology, and spinal biomechanical function in a sex-dependent manner." (PMID 32374776, 2020). "Mice with mutations in either the leptin gene or in the gene encoding the leptin receptor might develop severe obesity and high glucose levels." (PMID 32024487, 2020). "A subsequently initiated genetic analysis including sequencing of the leptin receptor gene revealed compound heterozygous variants as a cause of the severe early-onset obesity in both patients (c.2598-3_2607delTAGAATGAAAAAG and c.2227 T>C; c.1874G>A and c.2051A>C)." (PMID 33140236, 2020). "This form of leptin receptor deficiency results in obesity, hyperphagia, and hyperglycemia." (PMID 32152264, 2020). "Obesity-causing LEPR mutations are usually inherited in an autosomal-recessive manner." (PMID 32655492, 2020). "Many mutations in the LEP and LEPR genes have a major influence on metabolism, leading to obesity." (PMID 32982666, 2020). "Interestingly, it has been found that some people with specific mutations in LepR (LEPR 109KK) tend to prefer sweet food, implying the need of a personalized medical intervention when treating obesity." (PMID 32069871, 2020). "Therefore, we summarise the lessons learned from the two patients with LEPR deficiency and provide some recommendations for diagnosis and treatment of patients with suspected monogenic obesity, especially for patients with LEPR deficiency." (PMID 33140236, 2020). "C57BL/KsJ-db/db mice, characterized by obesity, infertility, hyperphagia, temporary hyperinsulinemia, hyperlipidemia, and hyperglycemia due to a leptin receptor mutation, were selected as an appropriate model for early-stage T2DM; these mice exhibit hepatic insulin resistance." (PMID 32796637, 2020). "For example, research conducted on people in some specific Asia-Pacific regions, concluded that the Q223R LepR SNP could be associated with obesity and type 2 diabetes." (PMID 32069871, 2020). "Third, NAFLD is strongly associated with obesity, which might trigger decreased expression of leptin receptor in liver tissue and insulin resistance." (PMID 33097057, 2020). "However, the mutation rates of five obesity-related genes in few cancer tissues were >0.05 (i.e., LEPR in SKCM (0.11), UCEC (0.07), and LUSC (0.07) and PCSK1 in SKCM (0.09) and UCEC (0.06))." (PMID 33299884, 2020). "Moreover, LEPR is present in atherosclerotic lesions, and ob/ob mice, which are leptin deficient, are protected from atherosclerosis in spite of obesity." (PMID 32824322, 2020).
Obesity (continued). "However, only a few genes are linked with the development of the monogenic form of obesity and these genes include, among others, leptin, leptin receptor, proopiomelanocortin, and prohormone convertase I." (PMID 31557979, 2019). "Furthermore, a study using a genetic model of obesity associated with a mutation in the leptin receptor (fa/fa Zucker rats) reported a possible link between obesity and CKD." (PMID 31289451, 2019). "Indeed, the leptin receptor mutation of db/db mice impairs the satiety feeling and leads to obesity around 4–5 weeks of age, which is followed by diabetic state with hyperglycemia and insulin resistance." (PMID 30792662, 2019). "Our study found that rs3790435 CC variants were associated with a lower risk of OSA in obese subjects, suggesting that LEPR might influence the occurrence of OSA with obesity." (PMID 31372721, 2019). "Specific variants of GNPDA2, PGC1α and LEPR genes have shown a strong association with Mexican population’s BMI, increasing the risk of obesity, although the control mechanisms of obesogenic genes expression during early development are still unknown." (PMID 31794592, 2019). "Many different models have been used to address mechanisms for how obesity and metabolic disease causes cardiac remodeling and HF development, including leptin or leptin receptor deficient mice and mice with pharmacologically induced (e.g., streptozotocin) diabetes." (PMID 31379826, 2019). "In addition to the HFD-fed mice, we conducted complementary experiments in db/db mice in which obesity is caused by a point mutation in the leptin receptor gene lepr, leading to spontaneous type 2 diabetes." (PMID 30612898, 2019). "Thus, leptin or the leptin receptor-deficient mice display common features of the immuno-metabolic dysfunction that are observed in obesity and diabetes mellitus." (PMID 31032262, 2019). "Therefore, deficiency of leptin or the leptin receptor leads an impaired energy expenditure and increased food intake, and thus to obesity." (PMID 31032262, 2019). "However, LepR deficiency in early life led to irreversible obesity via suppression of energy expenditure." (PMID 30694175, 2019). "The heterogeneity between the results of association between overweightness/obesity, and different variants of the LEPR gene in different populations may depend on the ethnicity or the differences in the gene-environment interaction." (PMID 30126176, 2018). "This review will concentrate on the original obesity gene, leptin (LEP) and its receptor (LEPR), together with a gene that has been identified as having variants of strong effect giving rise to both monogenic obesity and obesity in the general population, the melanocortin-4 receptor (MC4R)." (PMID 30121879, 2018). "Genetic variations in LEPR were already reported to be associated with a reduced capacity of leptin to regulate body weight and energy homeostasis, a process known as leptin resistance, which can lead to obesity-related phenotypes." (PMID 30126176, 2018). "Studies have reported the effects of nutrients, such as saturated fats, modulating the associations between these genetic variants, and overweightness and obesity to potentiate the obesogenic effect of the LEPR on the expression of genes linked to overweight/obesity." (PMID 30126176, 2018). "Also, the development of obesity in the Zucker fa/fa rat is caused by a genetic defect in the leptin receptor that is rare in humans." (PMID 29724010, 2018). "Additionally, the LEPR genes have been investigated for gene variants potentially related to the pathophysiology of obesity, T2DM, and its associated complications." (PMID 30583468, 2018). "Both the LEP and LEPR genes have been studied for polymorphisms that could possibly be related to the pathophysiology of obesity and its complications among specific ethnic groups." (PMID 30583468, 2018).
Obesity (continued). "Furthermore, leptin resistance at the adipocyte level due to local reduction of the leptin receptor has been related to metabolic disorders associated with obesity." (PMID 28744221, 2017). "Similarly to humans, obese mice and rats do not always develop T2D and kidney disease, even when they have a Mendelian mutation in a gene such as the leptin receptor (Lepr) that causes massive obesity." (PMID 29211750, 2017). "Acute LepR deficiency-induced obesity is one of the strongest stimuli for beta cell replication, and therefore might bypass the replication refractory period." (PMID 27003683, 2016). "LEPR deficiency in humans leads to morbid obesity and pituitary dysfunction, and polymorphisms in the LEPR gene have been associated with birth weight, obesity, and type II diabetes." (PMID 27330572, 2016). "Koletsky rats carry a nonsense mutation in the leptin receptor and possess interesting phenotypes, including obesity at 5 weeks of age, hypertriglyceridemia even with standard diet, hyperinsulinemia with normal blood glucose, and severe hypertension at 3 months of age." (PMID 27708685, 2016). "However, ZDF rat is an obese type 2 diabetes model with a point mutation in the leptin receptor, which makes it an ideal model for studying insulin resistance related to obesity." (PMID 27069931, 2016). "Similarly, LEPR 668 A/G + G/G carriers with a high fat total intake had 3.0 times higher risk of obesity (P = 0.002) and 4.1 times higher risk of cholesterol levels ≥200 mg/dL (P = 0.001) than those with a low intake of total fat <83 g/d." (PMID 26365669, 2015). "The aim of this study was to determine the interaction of dietary fat intake with the APOA2 (rs3813627 and rs5082), APOA5 (rs662799 and rs3135506) and LEPR (rs8179183 and rs1137101) polymorphisms and its relationship with obesity and dyslipidemia in young subjects." (PMID 26365669, 2015). "HFD feeding increased the hypothalamic mRNA expression of LEPR; an effect which the authors suggest may be a hallmark feature of hyperphagia and obesity development." (PMID 25792976, 2015). "The objective of this study was to analyze the interaction of a high fat diet with the APOA2 (rs3813627 and rs5082), APOA5 (rs662799 and rs3135506) and LEPR (rs8179183 and rs1137101) polymorphisms and its relationship with obesity and dyslipidemia in young subjects." (PMID 26365669, 2015). "Similarly, LEPR 668 A/G + G/G carriers with a high fat total intake had 3.0 times higher risk of obesity (p = 0.002) and 4.1 times higher risk of hypercholesterolemia (p = 0.001)." (PMID 26365669, 2015). "Our study also found that LEPR 668G allele carriers have an increased risk of hypercholesterolemia, also the interaction of allele with high-fat diet promotes hypercholesterolemia, hypertriglyceridemia and obesity." (PMID 26365669, 2015). "Recent studies in Europeans have suggested obesity related measures to be influenced by interactions between LEPR polymorphisms and a polymorphism of the tyrosine phosphatase 1B and ponderal index and future studies focusing on such “gene-gene” and “gene-environment” interactions are thus warranted." (PMID 26558825, 2015). "While the SHR/NDmcr-cp (SHR) rat model has been known to develop metabolic disorders due to its genetic deficiency in leptin receptor, the high-fat diet-induced obesity (DIO) model in C57BL/6 mice has been widely recognized as an obesity model driven by a dietary mechanism." (PMID 25793003, 2015). "In a previous study, similar results as in our study were found by crossing a mouse with a different mutation in the Apc gene (Apc1638N/+) with the C57BLKS-mLepdb/db mice, carrying a mutation in the leptin receptor gene (Ob-Rb) causing both obesity and diabetes mellitus." (PMID 26347815, 2015).
Obesity (continued). "The hyperphagia, reduced metabolism, and increased fat mass of our cKO mice is comparable to other mouse models of obesity such as leptin- and leptin-receptor-deficient mice, that develop obesity from early age, and a maturity-onset mouse obese model in which the melanocortin system was targeted." (PMID 25629159, 2015). "In addition, LepR tyrosine mutations-induced obesity also contributed to the reproductive abnormality of Y123F mice, because obesity can lead to decreased LH pulse amplitude and decreased excretion of progesterone metabolites." (PMID 26529315, 2015). "Among them, mutations in the leptin gene (ob/ob mice) or in the leptin receptor gene (db/db mice, fa/fa rats), leading to the deficiency of the related proteins, produce extreme obesity in rodents as well as in humans, due to hyperphagia, decreased energy expenditure, and insulin-resistance." (PMID 25352831, 2014). "Genetic predisposition to obesity associated to leptin (ob/ob mice) or leptin receptor (db/db mice) deficiencies appear to shape a microbiota specialized for enhanced dietary energy recovery with elevated abundance of Firmicutes and reduced abundance of Bacteroidetes compared with lean mice." (PMID 24733124, 2014). "Following the same lines of evidence, in a study of 284 volunteers with various levels of waist to hip ratio, the differences in blood pressure by LEPR variants remained significant after adjusting for the influence of obesity and body fat distribution, as well as insulin and leptin." (PMID 24772364, 2014). "A mutation in the leptin receptor has previously been reported to cause obesity in humans." (PMID 25273628, 2014). "To test this hypothesis, we measured viral clearance and lung injury severity in mice globally deficient in leptin receptor signaling (db/db), which exhibit many features of the metabolic syndrome including obesity, hyperglycemia, and insulin resistance." (PMID 25232724, 2014). "Since wild type mice heal wounds very rapidly and for the most part by wound contraction, we performed experiments in hyperglycemic db/db mice, which bear a spontaneous mutation in the leptin receptor gene and represent a model for human obesity and type 2 diabetes." (PMID 25068282, 2014). "In marked contrast to these studies that were mainly based on association between leptin and indicators of disease in obesity, surprisingly little is known regarding the leptin receptor on neutrophils and the functional responsiveness of these cells to this adipokine." (PMID 24066032, 2013). "Moreover, we determined the importance of leptin-mediated STAT3 activation for the development of cardiac hypertrophy in obesity by analyzing mice with targeted mutation of the STAT3 binding site within LepR." (PMID 23841921, 2013). "The homozygotes for the mutation (fa/fa) develop obesity because of a defective leptin receptor." (PMID 23573411, 2013). "Both db/db mice and ZF rats develop obesity due to the mutation of leptin receptor." (PMID 23028851, 2012). "Since tunicamycin is a synthetic and not a physiological stimulus of ER stress, continuing investigations should be extended to animal models of obesity in order to uncover to which extent ER stress- associated effects on the leptin – leptin receptor axis are of importance in-vivo." (PMID 22545089, 2012). "However, many further studies on the association between LEPR variants and obesity have been published since the last review in 2005, including studies on the interaction of these variants with sex or with other factors [e.g. 16]." (PMID 22028824, 2011). "Further, in contrast to the leptin receptor-deficient Zucker rat, where obesity develops independently of circulating leptin, the diet-induced obese rat directly reflects common forms of human obesity, where leptin, insulin, glucose, triglycerides and blood pressure are elevated." (PMID 21283658, 2011).